IDH1 (isocitrate dehydrogenase (NADP(+)) 1)
Diseases named in the same sentence as IDH1 in open-access papers (continued):
Sharing a sentence is not in itself a finding about the gene and the disease.
tumor (continued). "In the United States, the FDA approved ivosidenib for IDH1 mutations and pemigatinib, infigratinib, and futibatinib for FGFR2 fusions, alongside tumor-agnostic treatments for mismatch repair deficiency, NTRK fusions, ERBB2 amplifications, BRAF V600E mutations, and RET fusions." (PMID 39996880, 2025). "Tumors with IDH1 mutations had a trend toward more fibroblasts and were characterized by a closer proximity of tumor cells to CD4+ T cells, and between macrophages and multiple structural tumor microenvironment components as compared to other subtypes." (PMID 39969434, 2025). "The data suggest reversion of the IDH1 mutation is not the driver of PARPi resistance in the resistant tumor populations." (PMID 41357766, 2025). "The hypoxic microenvironment characteristic of the tumor further modulates these interactions, suggesting that targeting IDH-1, PHDs, or CCT may represent a promising therapeutic strategy." (PMID 41516249, 2025). "According to a retrospective study of patients with advanced iCCA who underwent chemotherapy, IDH1 mutations were observed in 14.5% of iCCA patients, and iCCA patients with IDH1 mutations appeared to have better tumor biological characteristics, including longer PFS, than those with IDH1 wild-type." (PMID 41008893, 2025). "RRBS analysis highlighted that regions associated with nucleic acid phosphodiester bond hydrolysis and DNA replication and repair were hypermethylated in IDH1 R132Q-expressing U87MG tumor xenografts versus R132H, reminiscent of DNA damage pathways hypermethylated in R132Q HT1080∗ tumors." (PMID 40188944, 2025). "EGFR and IDH1 were highly expressed in tumor cells, FAP and COL1A1 were confined to fibroblasts, CD68 and ITGAM marked macrophages, PECAM1 and CDH5 identified endothelial cells, OLIG2 and MOG were specific to oligodendrocytes, while CD4 and CD3D defined T-cell subsets." (PMID 41208987, 2025). "Our study found that GLSZM-based features played a similarly crucial role in IDH1 classification, suggesting that these metrics may not only differentiate molecular subtypes but also offer prognostic insights into tumor behavior and treatment sensitivity." (PMID 40299088, 2025). "For example, tumours harbouring NTRK fusions now have targeted options such as Larotrectinib and Entrectinib, while tumours with FGFR2 fusions can be treated with Pemigatinib and Futibatinib, and tumours carrying IDH1 mutations can be treated with Ivosidenib." (PMID 40723185, 2025). "Translational investigation highlights potential of IDH1 inhibition to alter tumor-immune interactions and provides hypotheses for future immune-checkpoint combinations." (PMID 41138165, 2025). "Thus, in the tumor models that we examined, we established that VPA diminished tumor growth in vivo and in vitro, but the murine model suggests a greater efficacy in IDH1 mutant tumors." (PMID 39149696, 2024). "Not only IDH-1, Ki-67 index is also an important biomarker of the tumor’s biological behavior." (PMID 39285364, 2024). "Here, we report the static and dynamic structural features that drive the distinct kinetic properties among tumor-relevant IDH1 mutants, capitalizing on the unusual active site attributes that allow R132Q to maintain conventional and enhance neomorphic activities." (PMID 38710674, 2024). "IHC for R132H IDH1 mutations on these three discordant cases confirmed positive staining in all cases, with low tumour content in two and high tumour content in a subsequent tissue block that had previously not had IHC testing completed." (PMID 37434550, 2024). "Furthermore, IDH1 and TERT mutations, 1p19q codeletion and MGMT methylation status were shown to be independently associated with tumour growth, providing molecular basis for the worse outcome." (PMID 38802734, 2024).
tumor (continued). "The tumor exhibited no IDH1, IDH2, TERT, H3, or BRAF mutation, and had no EGFR amplification, no MYB rearrangement, and a positive MGMT status." (PMID 39227460, 2024). "Patients with higher-grade tumours or/and IDH-WT gliomas exhibit worse NCF than patients with lower-grade or IDH-Mut tumours; those with IDH1-WT gliomas perform worse than those with IDH-Mut gliomas on learning, memory, processing speed, language, executive function, and dexterity tests." (PMID 39598176, 2024). "Compared to the initial resected tumor specimen, the recurrent tumor possessed a loss of heterozygosity of the 1p, 10q, 17q and 19q chromosomes, as well as a new C228T TERT promoter mutation, while the status of wild-type IDH1/IDH2 was unchanged." (PMID 39590169, 2024). "Over the years, it has been recognized that mutated forms of IDH1 and IDH2 may contribute to tumor development and serve as diagnostic markers." (PMID 39123479, 2024). "Additionally, [18F]-FACBC TBR was an excellent classifier for IDH1-wildtype tumor tissue (AUC: 0.83, 95% CI: 0.71–0.96)." (PMID 39061219, 2024). "Mutation analysis using WES data and CNV analysis using methylation classifier data from tumor tissues revealed no mutations in IDH1, IDH2, BRAF, or histone H3 genes (H3F3A, HIST1H3A, HIST1H3B, HIST1H3C, and HIST2H3C) in all tumors." (PMID 38605367, 2024). "In summary, we highlight discrete catalytic and structural features among two tumor-relevant IDH1 mutants, with the R132Q mutant serving as an invaluable tool to probe the journey through substrate turnover of two reactions that typically cannot be performed by the same enzyme." (PMID 38710674, 2024). "Therefore, the development of novel, highly selective small molecule inhibitors targeting IDH1 mutants is important to improve the efficacy of tumor therapy and reduce drug resistance." (PMID 39512821, 2024). "We demonstrated that among ATRX-deficient cell models, the presence of the IDH1 mutation has negligible impact on proliferation; however, upon intracranial implantation, mutant IDH1 significantly increases tumor aggressiveness, as indicated through a shorter survival and greater tumor penetrance." (PMID 38272925, 2024). "This suggests that the effectiveness of LEV as an antineoplastic agent may be influenced by the IDH1 status of the tumor." (PMID 39201639, 2024). "First, IDH1 and IDH2 mutations occur in highly restricted tumor types." (PMID 38763973, 2024). "However, TBR was acceptable for classifying ATRX-retained tumor tissue (AUC = 0.78, 95% CI: 0.63–0.93) and excellent for classifying IDH1-wildtype tumor tissue (AUC = 0.83, 96% CI: 0.7–0.95)." (PMID 39061219, 2024). "IHC analysis confirmed IDH1 R132H expression and ATRX loss in the nuclei of tumor cells." (PMID 39256867, 2024). "Focusing on the sequencing run with higher coverage, we observed that five mutations in cluster 1 (including IDH1 R132H) had VAFs over all tumor sections that were statistically indistinguishable." (PMID 39001492, 2024). "Circulating 2HG may be a surrogate biomarker of IDH1 or IDH2 mutation status in ICC and correlate directly with tumor burden." (PMID 39273177, 2024). "Little is understood of the mechanistic differences among tumor-driving IDH1 mutants." (PMID 38464189, 2024). "In the case of 38 CRD, the IDH1 mutation was revealed by both molecular methods, while the IHC method was not applicable to this sample due to the small quantity of tumor material." (PMID 38248076, 2024).
tumor (continued). "In addition, both in our IDH1 MT primary tumor cell lines and murine model, VPA inhibited transcription of FASN; hence we focused our attention on FASN." (PMID 39149696, 2024). "As molecularly guided treatment has been increasingly used to combat the heterogeneous tumour microenvironment of CCA, targeted therapies, such as ivosidenib for patients with IDH1 mutations and pemigatinib for patients harbouring FGFR2 fusions, respectively, have been approved for use in CCA." (PMID 37173994, 2023). "Moreover, IDH1 treatment enhanced CD8 T cell responses to several antigens shared by a variety of tumor types." (PMID 37161052, 2023). "The presence of circulating 2-HG has been hypothesized as an alternative biomarker of IDH1/2 mutational status in CCA, and its levels seems to correlate with tumor burden." (PMID 37168376, 2023). "Among possible causes of the better cognitive functioning of patients with IDH1-mut is brain plasticity which could be affected negatively by the greater tumour growth rate in IDH1-wt tumours, while remaining intact in less invasive IDH1-mut tumours." (PMID 37341199, 2023). "Furthermore, the mice bearing IDH1-mutant tumor expressed higher Atrogin-1 and MuRF1 compared with mice bearing IDH1-wt tumor." (PMID 37741882, 2023). "The process of adjusting antiepileptic drugs is carefully considered, especially in cases with high-risk factors such as tumor genetic marker (e.g. IDH1 mutant), tumor location (e.g. frontotemporal lobe), the occurrence of interictal epileptiform discharges on EEG, and tumor residual after surgery." (PMID 37407622, 2023). "It is suggested that IDH1 mutant and wild-type tumor cells may exhibit different phenotypes, during epithelial interstitial processes." (PMID 36819132, 2023). "The unique genetic profile (mutations in IDH1, IDH2, ATR-X, 1p/19q deletion) and complexities of the tumor microenvironment (hypoxic conditions, cell-cell/cell-stroma interactions) all contribute to the scientific challenges of constructing high fidelity LGG models." (PMID 37051530, 2023). "Even in cases where cancer cells can adapt to the loss of IDH1 over time, such as restoring IDH3 complex activity, they nevertheless remain significantly disadvantaged compared to tumours exhibiting wild‐type IDH1 for growth in vivo, further emphasizing the importance of IDH1 in PCa cells." (PMID 37086156, 2023). "By combining the differences in executive function impairment by IDH1 mutation status, we observed in the present study and the fact that tumor location alone would not sufficiently explain these differences." (PMID 36970174, 2023). "Due to incomplete patient data, we could not study specific previously reported predictors for developing IOS, such as the isocitrate dehydrogenase 1 (IDH1) status of the tumor, preoperative tumor volume, and tumor margins." (PMID 37711958, 2023). "It was recently shown that a lower level of DNA hypermethylation was observed for the IDH1 p.R132H variant compared to non-p.R132H variants, irrespective of tumour type." (PMID 37509266, 2023). "Probabilities of tumor recurrence after resection at 1, 4 and 7 years in patients with mIDH1/2 iCCA (10.5%, 45.3% and 45.3%, respectively) were significantly lower than those with wild-type IDH1 or IDH2 (41.7%, 71.5% and 81.3%, respectively)." (PMID 37168376, 2023). "IDH1 mutant tumours showed significant overexpression of MEG3." (PMID 37525401, 2023). "Tumor grade showed nonsignificance on NCF (p > .05) between the 2 IDH1 mutation subgroups of grade IV tumor patients." (PMID 36970174, 2023). "Preserved cognitive functioning might also be related to the tumour microenvironment, with more pronounced lymphocyte infiltration and programmed death-ligand 1 (PD-L1) expression in IDH1-wt tumours, or even to differences at the synaptic level." (PMID 37341199, 2023).
tumor (continued). "The IDH1 intronic mutation (c.414+9T>A) was previously reported in this HBL tumor by us; however, no missense mutations were detected in IDH1 and IDH2 genes in this tumor." (PMID 37273678, 2023). "Likewise, higher shape and directional heterogeneity in IDH1-wildtypes, could demonstrate that in IDH1-wildtypes, cancer spreads more throughout the surrounding brain tissue, reflecting poorer prognosis which might result in higher tumor cellularity and infiltration, causing FA and MD changes." (PMID 36653382, 2023). "We speculate that IDH1 may prolong anti-tumor CTL activity at sites of IDH1/NADP+ release by damaged tissue or killed tumor cells." (PMID 37161052, 2023). "Cell death resulting in IDH1 release could similarly impact responses to non-tumor antigens to augment or prolong normal CD8 T cell function." (PMID 37161052, 2023). "IDH1 mutations generate a gain-of-function conversion of α-ketoglutarate (αKG) to D-2-hydroxyglutarate (D2HG) that in turn inhibits DNA histone demethylases, resulting in hypermethylation-associated epigenetic tumor cell reprogramming." (PMID 37880243, 2023). "The lack of association between PD-1/FOXP3 with IDH1 mutational status of the tumor is probably one of the most fascinating findings of our study, which suggests that only a highly select subset of patients will benefit from combinatorial therapeutic options." (PMID 37621817, 2023). "This suggests that IDH1 substrate binding and/or catabolic activity is necessary for optimal T cell lysis, but whether IDH1 was tumor-derived was unclear." (PMID 37161052, 2023). "As a potential solution, rCBV was able to predict differences in IDH1 mutation and MGMT status, and tissue from hypercellular and hypervascular microfoci revealed greater expression of Ki‐67, HIF‐1a, CD31, and EGFR compared to tumor background." (PMID 36866773, 2023). "Although there is a significant reverse correlation between tumour malignancy and MEG3 expression in previous reports, we found that MEG3 activity differs between different cell lines and is mostly correlated with the IDH1 mutation status." (PMID 37525401, 2023). "The tumor was still IDH1 wild-type and MGMT promoter-unmethylated." (PMID 36831536, 2023). "Our analysis highlights that ASCETIC consistently identifies alterations in CALR, JAK2, and IDH1/2 genes as early events in tumor history, while NRAS represents an acquired secondary event, towards which evolutionary trajectories appear to converge during the progression of the disease." (PMID 37749078, 2023). "Similarly, IDH1 has been related to tumor development, and changes in IDH1 expression levels or gene mutations have been reported in several tumors." (PMID 38132097, 2023). "Because IDH1 is not normally secreted, this may occur through the release of active cytoplasmic IDH1 or IDH1R132H from CTL-lysed or otherwise ruptured tumor cells." (PMID 37161052, 2023). "We found a rare IDH1 mutation in CSF ctDNA from case 11, whereas a negative result was found in tumor DNA." (PMID 37822669, 2023). "Since the migration and proliferation of post‐surgical residual tumor cells are responsible for tumor recurrence, the GOx@MnCaP@fibrin gel has potential to inhibit IDH1 (R132H) tumor recurrence, which was demonstrated on a subcutaneous U87 tumor surgical resection model in this study." (PMID 38264686, 2023). "Patients with IDH1-mut tumours achieved impaired results on significantly lower number of tests." (PMID 37341199, 2023). "The analysis of IDH1 by immunohistochemistry is already part of the routine in several neoplasms." (PMID 37469494, 2023).
tumor (continued). "Moreover, according to our previous study, the analysis of our tumor tissue single-cell transcriptome data showed that the expression of IDH1 has a significant upregulation trend in cancer cell clusters (CSs)." (PMID 37958642, 2023). "In this study, we establish proof-of-principle for rapid colorimetric detection of the IDH1-R132H mutation in tumor samples in under 1 hour without the need for a nucleic acid extraction." (PMID 37733671, 2023). "Of critical interest is the long survival observed in 7 of the 37 vaccinated patients (2 with mutated IDH-1 and 5 wild type), who remain alive to this day (mean OS of 48 months, or 34 months after vaccination began) without evidence of tumor recurrence." (PMID 36831580, 2023). "Additionally, a positive correlation between ABCB1 methylation, the WHO tumor grade, and an IDH1 wild-type status has been observed." (PMID 36233525, 2022). "We further evaluated the relationship between IDH1 and various tumor-infiltrating immune cells." (PMID 35132321, 2022). "We measured the distance between the new contrast enhancement developing over time, and prior surgical lesioning, and evaluated tumor network changes in response to sequential resections by quantifying tumor cells and tumor networks with specific stainings against IDH1-R132H." (PMID 35706996, 2022). "The three IDH1 mutant tumours had HIF pathway scores similar to IDH1 wild type samples." (PMID 35419292, 2022). "Restricting our analyses to high-grade tumours and excluding tumours in the hands and feet, we found that patients whose tumour harboured both IDH1 and TERT mutations had significantly worse outcomes than those with an IDH1 mutation alone." (PMID 36042521, 2022). "We also conducted routine IDH1/2 tests for all tumor specimens." (PMID 35756637, 2022). "The IDH1 R132C has been detected previously in multiple tumor tissues." (PMID 35765075, 2022). "The mutant IDH1 with a neo-enzymatic activity could produce D-2-hydroxyglutarate whose accumulation in cells facilitates tumor proliferation and growth, increases the ROS level, and promotes hypermethylation in certain DNA sequence." (PMID 35135556, 2022). "OS was compared for a variety of subsets defined by the patient (age, KPS), tumor characteristics (MGMT promoter methylation and IDH1/2 mutation status), or anti-cancer therapy (number and cell composition of vaccinations received, TTF and/or bevacizumab use, and corticosteroid use)." (PMID 36517865, 2022). "We found that the high-risk group was significantly linked to older age, higher tumor grade, the wild status of IDH1, 1p/19q non-codeletion, unmethylated status of the MGMT promoter, and shorter survival." (PMID 36091778, 2022). "Potentially, PLEKHM3 may have a similar tumor suppressor role in GBM that is influenced by IDH1 or α-ketoglutarate; however, this would need to be experimentally investigated." (PMID 35877430, 2022). "Concerning tumor mutation, high-risk patients displayed a greater TMB than the low-risk patients, even though low-risk patients expressed more highly mutated genes (including the high frequency of mutant IDH1 and CIC)." (PMID 35535221, 2022). "In addition, although the volumes of IDH1+ tumors were statistically similar to IDH1- tumors, tumor growth varied between the groups and between radiotracer acquisitions." (PMID 35303961, 2022). "Timing analysis demonstrated that GD events tended to occur at a similar relative time in IDHwt and IDH1 cases implying that it could be an intermediate or late event in evolutionary timelines of both tumour groups." (PMID 36042521, 2022).